KRAS (KRas proto-oncogene, GTPase)
Diseases named in the same sentence as KRAS in open-access papers (continued):
Sharing a sentence is not in itself a finding about the gene and the disease.
cancer (continued). "Moreover, recent evidence showed that KRAS mutant cancer cells are also able to desaturate palmitate to sapienate via fatty acid desaturase 2 (FADS2), an event that confers additional independence to SCD-mediated FA desaturation." (PMID 36675307, 2023). "Thus, researchers have identified small molecule inhibitors with anticancer activity to treat KRAS-driven cancers." (PMID 37021044, 2023). "The presence of the KRAS mutation potentially influences many aspects of the management of cancer patients, regardless of chemotherapy and medical therapies." (PMID 36836752, 2023). "Correlation analysis between KRAS and functional status of cancer cells." (PMID 38206735, 2023). "Further, GSVA was carried out on the two PCa subtypes using the HALLMARKS50 gene set, and the results showed that some cancer‐promoting pathways, such as oestrogen response, epithelial‐mesenchymal transition and KRAS signalling, significantly enriched the subtypes with worse clinical outcomes." (PMID 37559353, 2023). "Differential signature and pathway analyses across the different groups showed a significant early activation of cancer-associated pathways (EMT and KRAS signaling) as well as of immune and inflammatory pathways, confirming the important role played by the immune system in malignant transformation." (PMID 37542347, 2023). "This can be anticipated as BRAF and KRAS are mutually exclusive in most cancers." (PMID 37404765, 2023). "In addition, SNAIL has EMT-independent oncogenic functions in cancer, and bypasses traditional oncogenic KRAS-induced senescence but blocks the retinoblastoma-controlled senescence pathway for cancer progression in pancreatic ductal adenocarcinomas." (PMID 37367036, 2023). "However, the administration of type IIb inhibitors to KRAS mutant cancers results in the activation of the MAPK pathway within these tumors, eventually leading to the occurrence of paradoxical activation." (PMID 37504287, 2023). "In the high-risk group, multiple cancer-related and ECM relative pathways were upregulated, which included pathways in cancer (p < 0.05), the cell cycle (p < 0.05), KRAS signaling up (p < 0.05), adherens junction (p < 0.05), ECM receptor interaction (p < 0.05), and notch signaling (p < 0.05)." (PMID 37727377, 2023). "Of 2715 patients with aNSCLC without other actionable driver mutations, 1344 (49.5%) had KRAS WT cancer, and 454 (16.7%) had KRAS G12C–positive cancer." (PMID 37069542, 2023). "Our group previously reported a KRAS signature upregulated across KRAS-driven cancers." (PMID 37210549, 2023). "GSL metabolism is therefore a vulnerability of KRAS mutant cancers that may have therapeutic implications." (PMID 36709325, 2023). "FSP1 inhibition and ferroptosis-inducing therapy could be a practical approach for KRAS-mutant cancer treatment." (PMID 37371948, 2023). "The potential role of CUR in regorafenib (RG)-treated KRAS mutant CRC cancer is indicated by the fact that CUR may target one additional gene other than mutant KRAS." (PMID 37175156, 2023). "Research in NSCLC has supported BRG1 as an instigator of KRAS-induced cancer." (PMID 36769189, 2023). "It is also reasonable to speculate that the combination of KRAS inhibitors and immune checkpoint inhibitors, including inhibitors of PD-1/PD-L1 or CD47/SIRPα, could provide synergistic benefits to patients with KRAS-driven cancers." (PMID 36413402, 2023).
cancer (continued). "A good method for determining whether KRAS status is a predictive factor is looking at the outcomes of various cancer treatments in randomized controlled trials." (PMID 37373999, 2023). "Oncogenic KRAS is the key driver oncogene for several of the most aggressive human cancers." (PMID 36443441, 2023). "However, our results challenge the notion that rare codons mechanistically underpin the predominance of KRAS mutant cancers." (PMID 36864243, 2023). "While the combination of the analysis of 5′/3′-end RET expression imbalance and variant-specific PCR allowed identification of RET translocations in approximately 2% of consecutive NSCLCs, this estimate approached 120/2361 (5.1%) in EGFR/KRAS/ALK/ROS1/BRAF/MET-negative carcinomas." (PMID 37445709, 2023). "It inhibits not only MAPK signaling activity but also mutated N‐ and Lysyl‐TRNA Synthetase (KRAS)‐driven signaling, and has shown efficacy in many MAPK‐driven human cancer cell lines and xenograft tumors with KRAS, Neuroblastoma RAS [Ras is a protein coding gene's name], and BRAF oncogenes." (PMID 36349142, 2022). "By calculating site-specific neutral cancer cell mutation rates in sequenced SCLC tumors, we can quantify the relative strength of selection driving prevalence of KRAS G12C in comparison to known SCLC drivers, gaining insight into the potential therapeutic efficacy of a KRAS G12C inhibitor." (PMID 36590382, 2022). "Both EGFR-mut and KRAS-mut cancers are now being treated with targeted therapy." (PMID 36612014, 2022). "Thus, their therapeutic efficacy depends on the genetic profile of the cancer patients (wild-type or mutant KRAS and BRAF)." (PMID 35705962, 2022). "Inhibition of ACLY in KRas-driven cancer cells in the absence of serum resulted in loss of cell viability." (PMID 36269753, 2022). "This suggests that higher ROS levels in mutant-RAS driven cancers enhance dependency on GSH production for survival and that SLC7A11 associated ferroptosis suppression may support mutant-KRAS driven cancer growth." (PMID 35280777, 2022). "RAS (KRAS, NRAS, and HRAS) represents the most frequently mutated gene family in human cancers." (PMID 35267628, 2022). "In addition, SOX2 expression and O-GlcNAcylation levels in KRAS-activated cancer cells were suppressed by dinaciclib." (PMID 35190631, 2022). "Targeting mutant KRAS is a major clinical challenge and the “holy grail” in cancer therapy." (PMID 35307764, 2022). "One-fifth of all human cancers, including 85%–90% of PDAC, harbor KRAS activating mutations." (PMID 35579947, 2022). "Besides playing a role in cancer-related pathways by regulating the expression of certain oncogenes and cancer suppressor genes such as KRAS, CDC6 promotes cancer progression as it is positively regulated by associated noncoding RNAs (e.g., lncRNA-CDC6)." (PMID 35537781, 2022). "Future studies will be necessary to clarify whether the newly identified metabolic role of NOP56 in KRAS-mutant cancer is related to its canonical role." (PMID 35039048, 2022). "Interestingly, the multifunctional, Ca++-binding S100A2 gene was one of few genes conserved in all 3 cohorts and S100P was conserved in the NEK and KRAS-mut cancers." (PMID 36612014, 2022). "Co-mutation of KRAS and KEAP1/NFE2L2 predicts worse survival to chemotherapy and immunotherapy, and Nrf-2-regulated ROS homeostasis has been linked to chemotherapy resistance in NSCLC and other cancers." (PMID 36591457, 2022).
cancer (continued). "The common patterns of reactivation seen with inhibitors that variously targeted only the mutant Ras protein, that targeted both mutant and wild-type KRAS or that targeted a key Ras effector showed the strong selective pressure for cancer cells to re-establish signal flow through the Ras network." (PMID 36065754, 2022). "A variety of signaling pathways including TNF-α, KRAS, IL-6/JAK/STAT3, IL-2/STAT5, epithelial-mesenchymal transition, oxidative phosphorylation, and mTOR were found to be significantly associated with TRPs in pan-cancer." (PMID 35831825, 2022). "Thus, the C1/C2 dimorphism on its own impacts peptide presentation and HLA-C-restricted T cell responses, with implications in disease, including adoptive T cell therapy targeting KRAS-G12D-induced cancers." (PMID 35587797, 2022). "By secreting IL-6, mutant KRAS cancer cells can activate Janus activated kinase 1 (JAK1) to induce the phosphorylation of the transcription factor signal transducer and activator of transcription 3 (STAT3) which is found in immune components such as macrophages of the TME." (PMID 36074553, 2022). "Moreover, examining gene expression data of KRAS-mutant cancer cells revealed that NOP56 silencing significantly enriched the mTOR gene signature." (PMID 35039048, 2022). "Indeed, KRAS-mutant mouse and human cancer cell lines displayed markedly increased baseline Il1r1/IL1R1 mRNA expression compared with WT cell lines, and significantly downregulated Il1r1/IL1R1 transcript levels after deltarasin treatment." (PMID 35327394, 2022). "In KRAS-addicted cancer cells, interrupting Ras-ERK signaling can induce apoptosis." (PMID 35114566, 2022). "Although KRAS inhibitor therapies exist, they have faced challenges due to the difficulty of targeting RAS directly and whether the KRAS mutant cancers retain dependence on KRAS, thus giving rise to a need for combinatorial strategies." (PMID 36430528, 2022). "On a mechanistic level, we report the existence of a KRAS/iRhom2/ERBB positive feedback loop that maintains oncogenic KRAS activity and might explain the potency of KRAS-induced cancers." (PMID 35971826, 2022). "We analyzed the specificity and robustness of this phenomenon as a drug target candidate, summarized recent efforts in exploiting macropinocytosis for drug delivery into KRAS mutant cancer, and discussed the opportunities, challenges and pitfalls of this strategy." (PMID 35154489, 2022). "Although insensitive to GAP-assisted hydrolysis, KRAS-mutated oncoproteins have measurable intrinsic GTP hydrolysis rates, could cycle between their active and inactive states in cancer cells, and are dependent on nucleotide exchange for activation." (PMID 35267628, 2022). "Moreover, combination therapy with DOT1L and SHP2 inhibitors was demonstrated to be effective in treating a specific subset of KRAS-mutant cancers characterized by a very poor prognosis." (PMID 35495127, 2022). "In fact, co-targeting autophagy and the MAPK pathway may be a potential therapeutic approach for KRAS-mutant cancers." (PMID 35883626, 2022). "In addition, the present study must be further validated in vitro and in vivo to determine the precise mechanisms of KRAS in diverse cancer types." (PMID 35563733, 2022). "Furthermore, SET/CIP2A overexpression was frequently observed in cancers with mutations in various oncogenes (e.g., EGFR, KRAS, NRAS, and BRAF)." (PMID 36463234, 2022). "In addition, an enhanced level of KRAS is considered a significant factor for cancer cell proliferation and tumorigenesis." (PMID 35546148, 2022). "In KRAS-transformed cancer cells, enhanced macropinocytosis was recognized as a metabolic adaptation under nutrient stress conditions, supporting the survival and proliferation of aggressive tumors by scavenging extracellular proteins, lipids and cell debris 12,15,16." (PMID 35154489, 2022).
cancer (continued). "GSVA analysis showed that the cancer region of TD2 (IAC) was enriched in KRAS signaling down." (PMID 36434043, 2022). "Interestingly, KRAS mutant cancer cells hijack CAFs to enhance oncogenic KRAS signaling and adapt their own metabolism in a reciprocal manner." (PMID 36612058, 2022). "In addition, several well-known PID-related genes are recognized as cancer-predisposing genes, including those found in immune dysregulation (e.g., ITK, KRAS), combined immunodeficiencies (e.g., JAK3, RECQL4) and phagocytic disorders (e.g., CDKN2A, CSF3R)." (PMID 36497424, 2022). "Some of the significant cancer hallmark terms are inflammatory response (CD14, CD69, IL10RA), KRAS signaling up (CD37, IL10RA, GPNMB), IL-6/JAK/STAT3 signaling (CD14, CSF2RB), Interferon Gamma Response (CD69, CSF2RB, IL10RA, VCAM1, SLAMF7), TNF-alpha Signaling via NF-kB (CD69)." (PMID 35486660, 2022). "Thus, ACA-28 and/or GT-7 were shown to induce apoptosis in cancer cell lines with different oncogenic mutations, ranging from HER2, BRAF, NRAS, and KRAS." (PMID 35203351, 2022). "The unsuccessful strategy to target KRAS for cancer therapy through FTIs might be explained by the existence of different RAS-mutant isoforms." (PMID 36012655, 2022). "KRAS is one of the most widely prevalent proto-oncogenes in human cancers." (PMID 34489556, 2022). "KRAS mutations mainly occur in the RAS domain, and many mutations lead RAS to continuously stimulate the downstream pathways, leading to the proliferation of cancer cells." (PMID 36713456, 2022). "Both HRAS and KRAS are frequently overexpressed in other cancer types as well." (PMID 36559011, 2022). "Studies have shown that KRAS-induced exosomes play multifaceted roles in maintaining lung immunosuppressive metastasis and bring about novel routes for intractable metastasis suppression, especially in chemotherapy-resistant cancers." (PMID 35663957, 2022). "Cancer cells depend primarily on the gene expression of KRAS or BRAF to survive." (PMID 36245983, 2022). "However, the ability of KRAS to be alternatively prenylated in response to farnesyl transferase inhibitor treatment rendered this approach ineffective for KRAS-mutant cancers, although these inhibitors have shown some efficacy in HRAS-mutant malignancies." (PMID 36334633, 2022). "In addition, a study has found that dasatinib sensitizes KRAS-mutant cancers to trametinib both in vivo and in vitro." (PMID 34737188, 2022). "Moreover, several reports have confirmed a link between oncogenic KRAS and the expression of the programmed death receptor-1 (PD-1) in cancer, which is an important molecule to target to avoid resistance to immunotherapy." (PMID 36430176, 2022). "Mutations in MAATP53, EGFR, FAT4, KMT2C, ARID1A, FAT1, and RNF213 were observed in the original cancer tissues, whereas KRAS and BRAF mutations were not identified." (PMID 35721089, 2022). "Statin-induced suppression of KRAS prenylation could cause dramatic ER stress via KRAS mutation, thus driving ICD of KRASmut cancer cells." (PMID 35784473, 2022). "The eighth edition of the AJCC Cancer Staging System is focused on the individual treatment and prognostic factors of CRC based on molecular biomarkers, such as BRAF, KRAS, and NRAS that are associated with chromosomal instability, mismatch repair, and microsatellite instability." (PMID 36142151, 2022). "KRAS mutation can also cause a reduction in the major histocompatibility complex (MHC) class I molecules, which negatively affects CD8+ cytotoxic T cell ability to identify cancer cells." (PMID 36430176, 2022).
cancer (continued). "Interestingly, one study found that when high-dose ascorbate was combined with fasting mimicking diet (FMD), also known as short-term starvation (STS), it preferentially decreased FTH protein expression in KRAS-mutant cancer cells in vitro." (PMID 35745630, 2022). "KRAS itself apart, to target the KRAS-driven malignant phenotypes, such as the metabolic vulnerabilities of KRAS mutant cancer mentioned in recent review, might represent another effective strategy." (PMID 36741696, 2022). "The revolution in the fighting against KRAS-mutant cancers occurred in 2012 when a breakthrough study showed that KRAS with G12C (glycine to cysteine) substitution can be targeted by a group of small molecules that bind covalently to the substituted cysteine in the Switch-II pocket of the protein." (PMID 36483040, 2022). "GSVA pathway analysis revealed differentially regulated cancer pathways between the three m5C-clusters, including KRAS-related pathways (MAPK-, mTOR-, EGF- and ERK-pathways), cell death pathways (TNFR1-, FAS- and death-pathways), and cancer-related pathways (Wnt-, Gleevec-, MET and CREB-pathways)." (PMID 36060802, 2022). "Among the three RAS isoforms (KRAS, HRAS, and NRAS), KRAS is the most frequently mutated isoform, and five mutations (G12D, G12V, G12C, G13D, and Q61R) are the most prominent RAS mutations observed in cancer patients." (PMID 36224343, 2022). "However, the studies of KRAS in pan-cancer are limited and we therefore focused on the expression and functions of KRAS in different cancer types." (PMID 35563733, 2022). "Moreover, the EpCAM-expressing cancer cells also showed positive staining for pERK, a KRAS downstream effector in PDAC 14,17." (PMID 35450328, 2022). "Moreover, combined treatment of selinexor with KRAS G12C inhibitors resulted in enhanced spheroid disintegration, reduction in the number and size of colonies formed by G12C-mutant cancer cells." (PMID 35573474, 2022). "Notably, these inhibitors rely on the intrinsic GTPase of mutant KRASG12C, i.e., the KRASG12C protein is still able to alternate between their active and inactive state, as GTP-bound KRAS is the predominant form in KRASG12C-mutant cancer cells." (PMID 35053550, 2022). "Elevated proteostress is also reported in cancers with amplified KRAS or MSI-high." (PMID 35307764, 2022). "Therefore, there is a strong possibility that KRAS-inhibited cancer cell-educated CAFs support a high degree of tolerance to KRAS inhibition observed in tumors." (PMID 36010567, 2022). "Among human cancers induced by mutations of RAS proteins, KRAS is the most frequently mutated oncogene, mainly occurring at the residues G12 and G13 and accounting for respective mutation rates of 86–96% in pancreatic cancers, 40–54% in colorectal cancers, and 27–39% in lung adenocarcinomas." (PMID 36080363, 2022). "This proposition was validated when we generated two KRAS G12C inhibitor–resistant cancer cell lines from KRAS G12C–mutant parental cells (MiaPaCa-2) and found that both AMG510- and MRTX1257-resistant cell lines were indeed sensitive to the XPO1 inhibitor selinexor." (PMID 35573474, 2022). "KRAS is recognized as one of the targets of cancer treatment." (PMID 35680848, 2022). "Interestingly, shortly after treatment, some cancer cells are sequestered in a quiescent state with low KRAS activity." (PMID 35251972, 2022).